EGFR (epidermal growth factor receptor)
Diseases named in the same sentence as EGFR in open-access papers (continued):
Sharing a sentence is not in itself a finding about the gene and the disease.
lung cancer (continued). "EGFR was readily detectable in membrane protein-enriched fractions from 7/9 cell models with HOS, IOR-MOS and OS-10 cells showing high expression even comparable to the EGFR-driven lung cancer cell line Calu-3." (PMID 26526352, 2015). "We analyzed gene expression profiles of gefitinib-resistant PC9M2 cells that were derived from gefitinib-sensitive lung cancer PC9 cells and do not have known resistance mechanisms including EGFR mutation T790M." (PMID 26268703, 2015). "Similarly to the effect of miR-145-5p, selective knockdown of OCT-4, EGFR, MYC, MUC-1 and the newly identified TPD52 impaired migration of lung cancer cells." (PMID 26440147, 2015). "Therefore, it is necessary to develop new EGFR PTK inhibitors and/or to target additional tumor promoting molecules to improve lung cancer treatment." (PMID 25730908, 2015). "The vast majority of patients with lung cancer fail to respond to tyrosine-kinase inhibitors against the epidermal growth factor receptor (EGFR), and no effective drug is available for small cell lung cancer." (PMID 26512779, 2015). "Given the high prevalence of lung cancer and the availability of targeted therapy, Chinese lung ADC patients without EGFR and KRAS mutations are recommended for HER2 and BRAF mutations detection, especially for those never smokers." (PMID 26102513, 2015). "Along these lines, there have been case reports of treatment naïve EGFR mutant SCLC12, 28, reinforcing the notion that the cell of origin of EGFR mutant lung cancers may have the potential to differentiate along a NE lineage." (PMID 25758528, 2015). "Since the recognition of EGFR as a therapeutic target, EGFR tyrosine kinase inhibitors (TKIs) have been widely used in treating NSCLC patients, which has been a major breakthrough for lung cancer treatment." (PMID 26503334, 2015). "Chemotherapy is currently the standard of care for ADC lung cancer patients in the absence of EGFR or other targetable molecular alterations (EML4-ALK), with erlotinib approved only for EGFR-mutated ADC patients in first-line treatment." (PMID 26247735, 2015). "This suggests that the molecular properties of EGFR are not stable and are likely to change during the process of lung cancer metastasis." (PMID 25663915, 2015). "Although these studies have demonstrated the capability of HSP90 inhibitors to down-regulate MET, they did not evaluate MET-mediated resistance to EGFR-TKI in lung cancer." (PMID 25780909, 2015). "To gain insight into the molecular mechanisms of EGFR-TKI resistance, we compared the expression profile of lncRNAs between gefitinib-sensitive and gefitinib-resistant human lung cancer cells by lncRNA microarray and found that thousands of lncRNAs were up-regulated in gefitinib-resistant cells." (PMID 26160838, 2015). "This approach has made significant headway in a number of cancers, such as breast and lung carcinoma, where alterations in the EGFR/ERBB pathways proved to be the main drivers that could be targeted with specific small molecules." (PMID 26395002, 2015). "Kaplan-Meier survival curves demonstrated significantly reduced survival for N39-positive patients in each subset grouped by age, stage, EGFR/KRAS/ALK alteration status, and smoking history, with the exception of patients with stage II lung cancer, presumably reflecting the reduced sample size." (PMID 25146220, 2014). "EGFR has become an important therapeutic target for the treatment of lung cancer especially in non-smokers, since more than 60% of NSCLCs express EGFR." (PMID 25028095, 2014). "We found that BTC could increase the proliferation, differentiation and movement of lung cancer cells, which could be down-regulated by PI3K, Erk, and EGFR inhibitors." (PMID 24629040, 2014).
lung cancer (continued). "In lung cancer, AXL was identified as a potential target for overcoming EGFR inhibitor resistance and combination of an AXL specific inhibitor (SGI-7079) with Erlotinib reversed Erlotinib resistance in a xenograft model of mesenchymal non-small cell lung cancer." (PMID 25193853, 2014). "Therefore, the evaluation of mRNA expression of CK19, EGFR and LUNX in the peripheral blood had important clinical value for the diagnosis of micrometastasis and the prognosis of lung cancer." (PMID 24396405, 2014). "Thus, molecular detection of lung cancers for the critical predictive biomarkers, ALK and EGFR, has become imperative to select right patients for target therapies in the clinical practice." (PMID 24667320, 2014). "Although previous studies have indicated that miR-133a can inhibit cell invasion and proliferation through downregulating EGFR, our in vitro lung cancer systems show that EGFR expression does not affect the invasion ability in CL1-5 and A549 cells." (PMID 24816813, 2014). "Tyr residues in EGFR of the lung cancer cells overexpressing DDX3X were not phosphorylated even in the presence of EGF." (PMID 25343452, 2014). "Until date, therapeutic decisions are heavily dependent on the histological subtype of lung cancer (SQC vs. non-SQC) and its molecular characteristics (e.g., EGFR mutation and ALK rearrangement states)." (PMID 24885169, 2014). "An S2RPGRMC1 inhibitor was active against cells expressing wild-type EGFR, but had no activity against lung cancer cells expressing EGFR mutants." (PMID 25594057, 2014). "We also confirmed that EGFR phosphorylation was suppressed after gefitinib treatment in all lung cancer cell lines with wtEGFR regardless of responsiveness to gefitinib." (PMID 24658031, 2014). "Although brain metastasis confers a poorer prognosis in lung cancer, this has never been documented in EGFR mutant tumors in the TKI era." (PMID 25548673, 2014). "In the current study, four lung cancer cell lines harboring wild-type epidermal growth factor receptor, comprising two squamous and two non-squamous cell lines, were used." (PMID 24396437, 2014). "In addition, oncogenically-activated mutant forms of EGFR and HER2 have been found in lung cancer, and contribute to the development of this disease." (PMID 25311788, 2014). "In other words, most of patients with lung cancer have wild-type EGFR (wtEGFR) which generally exhibits no response to gefitinib treatment." (PMID 24658031, 2014). "Our report shows that miR-147 recovered the EGFR-TKI gefitinib sensitivity of both colon cancer cell line HCT116 and lung cancer cell line A549 cells, which may be related to the inhibition of Akt and induction of other potential genes." (PMID 24454732, 2014). "Ongoing trials for recurrent or advanced NSCLC will test the efficacy of various combination therapies including EGFR inhibitors, second-generation tyrosine kinase inhibitors, dual MET/VEGFR2 inhibitor, and targeted drugs to different proteins disregulated in lung cancer." (PMID 24722523, 2014). "EGFR is overexpressed in more than 60% of NSCLC cases and considered as a driving force in lung adenocarcinomas, so targeting EGFR to inhibit EGFR-mediated pro-survival and anti-apoptotic signals through the MAPK/ERK and PI3K/AKT pathways would be an effective lung cancer treatment." (PMID 25375092, 2014). "Because the prevalence of adenocarcinoma with ALK rearrangement is low compared to EGFR mutation, studies investigating various characteristics of ALK-positive lung cancer do not gather enough participants to yield consistent results." (PMID 24885886, 2014). "Studies on the epidermal growth factor receptor (EGFR) signaling pathways and the therapeutic effects of EGFR-tyrosine kinase inhibitors (EGFR-TKIs) have recently proven that targeted therapy has a major role in the treatment of lung cancer." (PMID 25404271, 2014).
lung cancer (continued). "Interestingly, the three NSCLC samples with the highest SRSF2 and phospho-SRSF2 scores all displayed a drop in the HER1/EGFR "last exon > e20" transcript, as determined by quantitative RT-PCR, similarly to what occurred in lung cancer cells." (PMID 24428911, 2014). "A meta-analysis comparing EGFR-TKIs with chemotherapy as second-line therapy for wild-type EGFR lung cancer patients was presented in part at the 2013 ASCO annual meeting and also demonstrated chemotherapy had superiority in PFS over EGFR-TKIs for EGFR M− patients." (PMID 25029199, 2014). "The authors also reported on 6 NRAS mutant lung carcinoma cell lines and their sensitivity to the MEK inhibitors selumetinib and trametinib and their resistance to erlotinib (EGFR-TK inhibitor), crizotinib (ALK/MET/RON/ROS1 inhibitor) and linsitinib (IGF-1R inhibitor)." (PMID 25277205, 2014). "EGFR-Thr654 and EGFR-Ser1046 phosphorylation decreased upon application of an AURKA inhibitor, but only in EGFR-L858R mutant cell lines, which raised the possibility of the therapeutic application of AURKA inhibitors in lung cancer patients." (PMID 23520446, 2013). "The co-activation of RTKs and SFKs observed in clusters containing EGFR and MET suggested the hypothesis that functional synergy between two or more tyrosine kinases plays a role in lung cancer development." (PMID 23300999, 2013). "The EZR-ROS1 fusion gene was specifically detected in lung cancer specimens of female never-smokers without EGFR, KRAS, and ALK alterations." (PMID 23418494, 2013). "For lung cancers, the genomic panel comprises of ALK, EGFR, KRAS and BRAF." (PMID 23863689, 2013). "Our results suggest that multiple targets of lestaurtinib could be active and important in the lung cancer cells studied, as we observed reductions in ERK phosphorylation at concentrations below those necessary for inhibition of EGFR phosphorylation." (PMID 24189400, 2013). "In clinical trials, however, several of these irreversible EGFR-TKIs failed to meet their primary endpoints in EGFR-TKI-refractory lung cancer and induced severe toxicities, such as diarrhea, skin rash/acne, stomatitis, and nail effects." (PMID 24386407, 2013). "Co-activation of MET, AXL, ERBB2, and EPHA2, and co-activation of DDR1 with EGFR, DDR2, HCK, PDGFRA, and FGR is evidence that simultaneous activation of multiple tyrosine kinases may be common in lung cancer." (PMID 23300999, 2013). "Combinational targeting on both EGFR and STAT3 may enhance the efficacy of gefitinib or other EGFR TKIs in lung cancer." (PMID 24280348, 2013). "In conclusion, we showed here that bufalin could reverse HGF-induced resistance to EGFR-TKIs by inhibiting Met/PI3K/Akt pathway and activating death signaling in EGFR mutant lung cancer cells." (PMID 23533466, 2013). "Concurrent activation of ALK and EGFR signaling pathways has been reported in the lung cancer cell lines, and these cell lines could only be suppressed by dual inhibition of both ALK and EGFR." (PMID 23951022, 2013). "Interestingly, studies on different lung cancer cell lines suggested that NCI-H292, a pulmonary MEC cell line that has wild-type EGFR, is more sensitive to gefitinib than other wild-type EGFR non-small cell lung cancer cell lines." (PMID 24303221, 2013). "These genes, EGFR, COL4A1, and CDK4 all shared the ‘pathways to cancer’ annotation; and EGFR and COL4A1 were shown to be involved specific cancers such as glioma, melanoma, lung cancer, bladder cancer, and pancreatic cancer." (PMID 23737970, 2013). "Finally, AP2M1, found in lung cancer cell line TAP and also identified with wild-type EGFR in AALE cells, was chosen as a representative member of adapter proteins important in EGFR endocytosis." (PMID 24189400, 2013).
lung cancer (continued). "Adenocarcinomas are now regarded as the most common lung carcinoma subtype, constituting approximately 40% of all non-small cell lung cancers (NSCLC) and molecular analysis of EGFR exons 18, 19, 20, 21 is recommended in all adenocarcinoma or lung tumors with an adenocarcinoma component." (PMID 24376723, 2013). "Treating lung cancer cells with EGCG or C75 induced apoptosis and affected EGFR-signaling." (PMID 22769244, 2012). "The clinical features of lung cancer that harbors EML4-ALK include light- or never-smokers, younger age, adenocarcinomas with acinar pattern or signet ring adenocarcinoma, and a lack of EGFR or KRAS mutations." (PMID 23181703, 2012). "This type of analysis predicts how the lipid metabolic pathway may functionally interact with EGFR, MET, and other biological processes in lung cancer cells, and offers an insight into the roles of EGFR and MET inhibition in lung cancer therapeutics." (PMID 22211244, 2012). "Although targeting MUC1 and EGFR individually have been proven to be effective in treating a portion of lung cancer patients, chemoprevention against these two factors has not been studied." (PMID 22457794, 2012). "Our analysis revealed three distinct MCRs of gain on 7p, however none encompassed the lung cancer oncogene, EGFR, located on chromosome 7p11.2." (PMID 22412972, 2012). "The authors found that genetic or pharmacologic inhibition of NFκB signaling increased sensitivity to erlotinib but not to chemotherapy in several models of EGFR mutant lung cancer." (PMID 22970367, 2012). "Recent studies have demonstrated that lung cancers harboring ALK rearrangements do not respond to EGFR-specific tyrosine kinase inhibitors, but benefit from a small molecule inhibitor targeting the ALK kinase (ie, crizotinib [Xalkori®, Pfizer, Inc.])." (PMID 23198868, 2012). "Of note, a number of key pathways activated in lung cancer in never smokers, including EGFR, Akt, MAPK and STAT3, are activated in this mouse model." (PMID 23251519, 2012). "Tyrosine kinase inhibitors against the epidermal growth factor receptor (EGFR) have been developed and although the vast majority of patients with lung cancer failed to respond, a minority showed dramatic tumor shrinkage." (PMID 22272264, 2012). "Early trials of EGFR inhibitors combined with analogues in glioblastoma patients did not disclose any positive results and lung cancer patients resistant to EGFR inhibitors showed toxic effects that required discontinuation or dose reductions in some patients." (PMID 22408430, 2012). "In contrast, neither gefitinib-sensitive nor gefitinib-resistant lung cancer cells carrying EGFR mutants showed BCRP/ABCG2 expression." (PMID 21731744, 2011). "We found that the EGFR–TKI gefitinib did not inhibit EGFR phosphorylation in lung cancer cells with MET amplification." (PMID 21847121, 2011). "The findings on gene expression highlight some of the complex interconnections and crosstalk between different components of the EGFR and NF-κB pathways, which has not been previously explored in lung cancer." (PMID 21951562, 2011). "In conclusion, our results suggest that EGFR, HER2, HER3, and RET are trans-phosphorylated by MET and promote cell proliferation and survival or cell migration as heterodimerisation partners of MET in lung cancer cells with MET amplification." (PMID 21847121, 2011). "Mutations in EGFR and KRAS are mutually exclusive in both human and murine NSCLC, and EGF stimulation would not be expected drive Kras mutant models of lung cancer." (PMID 21699731, 2011). "Research on EGFR's pathogenesis have been focused on lung cancer and have not discovered its link to heart diseases." (PMID 22034985, 2011).
lung cancer (continued). "Therefore, the aim of this study was to explore the anticancer activity of ART and to investigate the effects of ART on the expression of EGFR and ABCG2 in A549 human lung cancer cells and a mouse xenograft model." (PMID 22183882, 2011). "EGFR expression was negative in paracancerous and normal tissues, which was significantly lower than that in lung cancer tissue (46%)(P < 0.05)." (PMID 21385353, 2011). "Together, these results suggested that MET, EGFR, HER2, and HER3 activate AKT and ERK signalling pathways and promote cell proliferation and survival in lung cancer cells with MET amplification, whereas MET, HER2, and RET activate the STAT3 signalling pathway and promote cell migration." (PMID 21847121, 2011). "Extrinsic differences independent of the IGF-1R pathway, such as her2/neu or EGFR activation for breast or lung cancer, respectively, likely play a larger role since those pathways often serve as the primary regulator of their malignant phenotype." (PMID 24212944, 2011). "In addition to the cross talk of PGE2 and EGFR pathways, PGE2 is able to induce proliferation of colon and lung cancer cells through activating MAPK in an EGFR-independent manner in vitro." (PMID 24213116, 2011). "For advanced colorectal and lung cancers, patients currently are screened for mutations in the KRAS gene as therapy targeting EGFR is not effective when these tumors harbor mutations in the pathway downstream of EGFR." (PMID 21072204, 2010). "In the NCI-60 cell lines, EGFR mutation was detected only in the SK-MEL-28 melanoma and RPMI-8226 myeloma lines, but not in any lung cancer cell lines." (PMID 20808922, 2010). "They later observed that an AKT inhibitor when combined with MEK inhibitors, failed to induce apoptosis in human lung cancer cells with mutant EGFR although these cells were sensitive to the combination of PI3K and MEK inhibitors." (PMID 21124782, 2010). "In addition, previous clinical trials have demonstrated that both EGFR and HER-2 genes are amplified in lung cancer, resulting in the overexpression of these proteins." (PMID 20459769, 2010). "Here, we tested whether genomic gains in six specific loci, TP63 on 3q28, EGFR on 7p12, MYC on 8q24, 5p15.2, and centromeric regions for chromosomes 3 (CEP3) and 6 (CEP6), may provide further value in the prediction of lung cancer." (PMID 19547694, 2009). "Molecular correlates of clinical response/nonresponse to EGFR-targeted therapies have been identified for colon and lung cancers." (PMID 19636423, 2009). "We selected six DNA targets commonly amplified in lung cancer including two centromeric probes (CEP3 and CEP6) and four probes to areas of frequent genomic amplification, i.e. 3q28 (TP63), 5p15.2 (D523 and D5S721 markers), 8q24 (MYC), and 7p12 (EGFR)." (PMID 19547694, 2009). "It is important to note that the GEPR generated in lung cancer cell lines and was not dependent on either KRAS or EGFR mutation status." (PMID 19439077, 2009). "Tyrosine kinase inhibitor gefitinib is effective against lung cancer cells carrying mutant epidermal growth factor receptor (EGFR); however, it is not effective against lung cancer carrying normal EGFR." (PMID 19178753, 2009). "We hypothesised that MET signalling plays a key role in lung cancer oncogenic signalling and optimised therapy targeting MET would be effective as a treatment strategy in the face of EGFR-TKI resistance." (PMID 19238632, 2008). "A549 is an extensively studied lung cancer cell line and is known to have KRAS mutation but not any EGFR kinase domain mutations." (PMID 19238632, 2008).